TYRP1 (tyrosinase related protein 1)
Diseases named in the same sentence as TYRP1 in open-access papers (continued):
Sharing a sentence is not in itself a finding about the gene and the disease.
tumor (continued). "Furthermore, melanocyte differentiation genes, including MITF, TYR, and TYRP1, were upregulated significantly by FR in class 1 relative to class 2 tumor biopsy samples." (PMID 33577798, 2021). "Furthermore, tyrosinase and TYRP1 correlates inversely with tumor stage and its progression to the amelanotic phenotype." (PMID 27206672, 2016). "However, RNAseq from bulk tumors underrepresents the tumor content compared to cell lines and may underestimate the number of patients with TYRP1 overexpression." (PMID 38336975, 2024). "However, a relatively uniform minimum of 80% CD47 repression achieved through CRISPR interference (CRISPRi), combined with the ineffective monoclonal antibody (anti-Tyrp1), enables phagocytosis to dominate net growth, triggering an effective anti-tumor immune response." (PMID 38543240, 2024). "The early development of neutralizing ADAs in most participants, together with the low doses assessed in the study, might have impacted the opportunity to observe clinical activity with the molecule, even though preclinical data for TYRP1-TCB demonstrated tumor shrinkage." (PMID 38577337, 2024). "After OV-induced oncolysis and immune infiltration, ICIs may have additional neoantigens (or non-mutated antigens such as TYRP1) available for a more robust tumor-specific immune response." (PMID 38022659, 2023). "Additionally, incorporation of TYRP1 may focus the immune response more in the tumor, and less in off-target sites, while also improving T cell immunity." (PMID 38022659, 2023). "In addition to the effect of the abrogation of HDAC6 on the expression of immunosuppressive proteins, it has been shown that the genetic and enzymatic inhibition of HDAC6 induces the expression of MHC class I as well as several tumor- associated antigens including gp100, MART1, TYRP1, and TYRP211." (PMID 30992475, 2019). "To investigate the biological relevance of these three different classes of TYRP1 peptides, we tested 4 of each of the Shared, B16-F10-(AIRE)-Unique and B16-F10-(AIRE)-Longer class as vaccines against parental B16-F10 tumours." (PMID 39606441, 2024). "RO7293583 (anti-TYRP1/CD3 T-cell engager) binds to both CD3 on cytotoxic T lymphocytes (CTLs) and TYRP1 found on TYRP1-expressing tumor cells." (PMID 39943991, 2024). "IT administration ensures virus delivery to the tumor to initiate an infection and prime the immune cells while IV administration delivers VSV-IFNβ-TYRP1 to other metastatic lesions." (PMID 38022659, 2023). "Tyrosinase-related protein 1 (Tyrp1) is a melanocyte-specific biomarker whose expression in the lung is restricted to B16F10, which provides a quantitative measure of tumor development." (PMID 36329436, 2022). "TYRP1 mRNA, independently of its protein‐coding activity, sequestering through its 3′‐UTR a microRNA (miR‐16) and thus dampening the tumor suppressor activity of miR‐16 itself." (PMID 30499222, 2019). "Only in 1 cell was there found a gain of the chromosomal region 9p24.3–9p23, where PTPRD is located, which has been reported to act like a tumor suppressor gene in NB, in addition to other genes, indicated to be related to cancer (i.e., JAK2, RLN2, TYRP1)." (PMID 30791380, 2019). "Antimetastatic RARβ2 signalling, direct or indirect, results in an elevation of expression for genes such as tumor-cell antigens (CTAG1 and CTAG2), those involved in innate immune response (e.g., RIG-I/DDX58), and tumor suppressor functions (e.g., TYRP1)." (PMID 16255778, 2005). "Our profiles indicate that RARβ2 induces a number of tumor suppressor functions (NDRG1, RPL10, and ST18) and known metastasis suppressors (NDRG1 and TYRP1)." (PMID 16255778, 2005). "(i) Tumor growth at early timepoints where growth is still linear shows suppression of tumors comprised of B16F10 CD47 KO cells pre-opsonized with convalescent sera and anti-Tyrp1, compared to mouse IgG2a isotype controls." (PMID 38805560, 2024).
tumor (continued). "Importantly, the epitope recognized by the 20D7S antibody is conserved between the human and murine TYRP1 protein, allowing evaluation of the human CAR construct against syngeneic tumor models." (PMID 38336975, 2024). "The potential of TYRP1 as a therapeutic target has been explored previously in a phase 1 study evaluating the monoclonal antibody flanvotumab (IMC-20D7S), which showed that this treatment was well tolerated and had evidence of anti-tumor activity." (PMID 38577337, 2024). "HLA-DR did not correlate with MITF at mRNA or protein level, but the HLA-DR IHC score was positively correlated with the TYRP1 IHC score and was lower in tumours with no-low pigmentation compared to moderately and heavily pigmented tumours." (PMID 37240204, 2023). "Moreover, well-known target proteins of MITF in melanogenesis such as TYRP1, DCT, and TYR1 proteins were positivity regulated in Opn4WT tumor, and therefore, strongly suggest a reduction of MITF signaling in Opn4KO tumor." (PMID 35562405, 2022). "A new bispecific antibody targeting T-cell CD3 and TYRP1, a protein overexpressed in over 50% of mM tumor cells, allows directs tumor–T-cell engagement without requiring MHC presentation or an APC." (PMID 35453572, 2022). "In vitro experiments revealed that knockdown TYRP1 promoted the expression of HLA-A, B, and C. These findings indicate that inhibition of TYRP1 potentially promote the antigen presentation of MHC class I in tumor cells." (PMID 33869027, 2021). "The high level of TYRP1 mRNA promotes proliferation and tumor growth irrespective of the protein level." (PMID 31624899, 2020). "Despite the absence of radiographic tumor shrinkage, biological activity was evident; Smith reported dose-dependent Tyrosinase Related Protein 1 (TYRP1)-specific T-cell expansion and epitope spreading, with two patients subsequently deriving durable benefit from immune-checkpoint blockade." (PMID 41598579, 2026). "Meanwhile, a UCLA group showed that >90% of uveal melanoma tumors express TYRP1; optimized TYRP1-specific CAR-T cells were detected (even at low antigen density), halted the growth of patient-derived xenografts, and caused no off-tumor toxicity, clearing the way for a phase I trial." (PMID 41598579, 2026). "Since MEK inhibition resulted in the increased expression of the TA99 mAb target itself (TYRP1), as well as other melanosomal antigens, we treated B16 and YUMM1.9 subcutaneous tumor bearing mice with a combination with trametinib and TA99 and followed tumor growth." (PMID 33520112, 2021). "The lack of melanin production in B78 due to a mutation in the tyrosinase-related protein 1 gene, minimizes autofluorescence in the green and red channel during optical imaging and enables better visualization of the dynamics of live GFP+ T-cell movement at the tumor site." (PMID 32793206, 2020). "Nevertheless, the expression of TYRP1 in tumors was lower for both LUAD and LUSC compared to adjacent normal tissue, implying a lack of tumor specificity of this gene in these tumor types." (PMID 39943991, 2024).
cancer (37 papers, 2013 to 2026). A tumor composed of atypical neoplastic, often pleomorphic cells that invade other tissues. "To test where these de novo serum antibodies functionally promote macrophage-mediated phagocytosis, we performed conventional 2D phagocytosis assays in which cancer cell suspensions were opsonized with sera (or anti-Tyrp1 or mouse IgG2a isotype as controls)." (PMID 37066426, 2024). "To further explore the broad applicability of an anti-TYRP1/CD3 bi-specific across various cancer types we leverage data from the publicly available TCGA dataset." (PMID 39943991, 2024). "Both convalescent sera and anti-Tyrp1 provide similar survival benefits, suggesting potent de novo IgG opsonization and anti-cancer function." (PMID 38805560, 2024). "Although these macrophages seemed poised for anticancer activity, the cancer cells showed decreased binding of anti-Tyrp1 and ~20% larger size in flow cytometry." (PMID 38805560, 2024). "The C0 TYRP1+ subtype was generally enriched in early-stage tumors (Group I), confirming its probable role in melanogenesis and tolerance to oxidative stress during the early stages of carcinoma." (PMID 41383633, 2025). "To test whether these de novo serum antibodies functionally promote macrophage-mediated phagocytosis, we performed conventional 2D phagocytosis assays in which cancer cell suspensions were opsonized with sera (or anti-Tyrp1 or mouse IgG2a isotype as controls)." (PMID 38805560, 2024). "Such cancer cell changes might explain why standard 2D phagocytosis assays show BMDMs attached to rigid plastic engulf relatively few anti-Tyrp1 opsonized cancer cells pre-treated with MPS1i versus DMSO." (PMID 38805560, 2024). "Further work is required to confirm these potential roles of TYRP1 in cancer development." (PMID 33067454, 2020). "Mice that are re-challenged with chromosomally stable CD47 KO tumors (and without exogenous anti-Tyrp1 opsonization) show increased median survival and increased immune infiltrate, further supporting the hypothesis of newly generated anti-cancer acquired immunity." (PMID 38805560, 2024). "Mice that are re-challenged with chromosomally stable CD47 KO tumors (and without exogenous anti-Tyrp1 opsonization) shows increased median survival and increased immune infiltrate, further supporting the hypothesis of newly generated anti-cancer acquired immunity." (PMID 37066426, 2024). "In addition, alphavirus-based DNA vaccination against a non-mutated tumor-associated self-antigen (tyrosinase-related protein-1, TRP-1) is severely impaired in RNase L null mice, indicating that RNase L plays an important role in the host immune system against cancer." (PMID 24324683, 2013).
neurodegenerative disease (3 papers, 2010 to 2023). A disorder of the central nervous system characterized by gradual and progressive loss of neural tissue and neurologic function. "In our ongoing work, we intend to further test the links between Tyrp1 and Lyst-mediated ophthalmic disease, and to dissect the neurodegenerative disease uncovered in D2.Lystbg-J mice." (PMID 20617205, 2010).
TYRP1 also shares sentences with these, for which no sentence is quoted: infection (27 papers); Alzheimer disease (8); glioblastoma (7); Cognitive impairment (6); glioma (6); cognitive decline (3); colon cancer (3); dementia (3); Griscelli syndrome (3); mucosal melanoma (3); periodontitis (3); polymyositis (3); viral infections (3); amyloid (2); anterior synechia (2); Atrophy (2); Chediak-Higashi syndrome (2); cutaneous leishmaniasis (2); Genetic Disorders (2); liver fibrosis (2); lysosomal storage disease (2); memory impairment (2); microphthalmia (2); neuroblastoma (2); ocular hypertension (2); Parkinson disease (2); periodontal disease (2); rheumatoid arthritis (2); Senile plaques (2); synucleinopathy (2).
A further 75 diseases each share a sentence with TYRP1 in 2 papers or fewer.